PTH2R (parathyroid hormone 2 receptor)
Description:
This is a specific receptor for parathyroid hormone. The activity of this receptor is mediated by G proteins which activate adenylyl cyclase. PTH2R may be responsible for PTH effects in a number of physiological systems. It may play a significant role in pancreatic function. PTH2R presence in neurons indicates that it may function as a neurotransmitter receptor (By similarity).
Synonyms: PTHR2
Tractability: Small molecule: a structure with a bound ligand is known. Antibody: its Gene Ontology location is reachable by antibodies, with high confidence; UniProt places it where antibodies can reach, with medium confidence; UniProt predicts a signal peptide or a membrane-spanning region.
Target class: Membrane receptor; Parathyroid hormone receptor; Peptide receptor (family B GPCR); Family B G protein-coupled receptor
Gene: Protein-coding gene on chromosome 2 (208,359,714 to 208,854,503, forward strand). Ensembl gene ENSG00000144407.
Subcellular location: Cell membrane
Pathways (Reactome):
Signal Transduction: Class B/2 (Secretin family receptors); G alpha (s) signalling events
Gene Ontology:
Molecular function: protein binding; G protein-coupled peptide receptor activity; parathyroid hormone receptor activity; peptide hormone binding; G protein-coupled receptor activity; transmembrane signaling receptor activity
Biological process: adenylate cyclase-modulating G protein-coupled receptor signaling pathway; G protein-coupled receptor signaling pathway; positive regulation of cold-induced thermogenesis; cell surface receptor signaling pathway
Cellular component: plasma membrane; membrane
Genetic constraint (gnomAD): Loss-of-function variants: 55 observed, 52.85 expected, observed/expected ratio (o/e) 1.04, 90% interval 0.84 to 1.3. The upper end of that interval is the gene's LOEUF score, 1.3, which puts it in group 5 of 6, group 1 being the genes least tolerant of losing a copy. Missense variants: 695 observed, 650.31 expected, observed/expected ratio (o/e) 1.07, 90% interval 1 to 1.14. Synonymous variants: 248 observed, 233 expected, observed/expected ratio (o/e) 1.06, 90% interval 0.96 to 1.18.
Homologues: Orthologues: chimpanzee PTH2R (99% identical), macaque PTH2R (98% identical), pig PTH2R (89% identical), dog PTH2R (86% identical), mouse Pth2r (83% identical), rat Pth2r (81% identical), guinea pig PTH2R (79% identical), tropical clawed frog pth2r (72% identical), zebrafish pth2ra (60% identical), zebrafish pth2rb (59% identical). Paralogues in human: PTH1R (49% identical), VIPR1 (31% identical), SCTR (30% identical), ADCYAP1R1 (27% identical), GLP2R (27% identical), GIPR (26% identical), GCGR (25% identical), VIPR2 (25% identical), GLP1R (25% identical), CALCR (24% identical), GHRHR (24% identical), CALCRL (23% identical), and 30 more.
Diseases named in the same sentence as PTH2R in open-access papers:
PTH2R is named in the same sentence as 25 diseases in open-access papers, as found by Europe PMC text mining. Sharing a sentence is not in itself a finding about the gene and the disease. The quoted sentences say what the papers report.
ovarian carcinoma (5 papers, 2019 to 2025). A malignant neoplasm originating from the surface ovarian epithelium. "Additionally, PTH2R protein has been implicated in the proliferation and migration of ovarian cancer cells." (PMID 41154849, 2025). "Clinical data analysis indicates that the PTH2R gene is highly expressed in ovarian cancer cells, and it participates in the proliferation, invasion, and metastasis of ovarian cancer cells." (PMID 41585794, 2025). "In conclusion, the PTH2R gene was found to be involved in the proliferation, invasion, and metastasis of ovarian cancer." (PMID 35410353, 2022). "In this study, the combined TCGA-OV data set and the GSE18520, GSE66957 data sets showed that PTH2R was significantly elevated in ovarian cancer tissues." (PMID 35410353, 2022). "After experimental verification, we found that knocking down the expression of PTH2R can inhibit the proliferation, invasion and migration of tumor cells.PTH2R is expected to become a new molecular marker for ovarian cancer." (PMID 35410353, 2022). "In this study, PTH2R was found to be highly expressed in ovarian cancer through bioinformatics methods, combined with the GEO and TCGA databases." (PMID 35410353, 2022). "Bioinformatics analysis and experimental verification revealed that the high expression of PTH2R can promote the growth, invasion, and metastasis of ovarian cancer." (PMID 35410353, 2022). "First, we tested the knockdown efficiency of PTH2R in ovarian cancer cells, and found that knocking down with sh-PTH2R reduced the expression of PTH2R more than half in A2780 and SKOV3 cell." (PMID 35410353, 2022). "The final selection contained four receptors (GPR39, LPAR3, OXTR and PTH2R) with strong expression in ovarian cancer tissue and generally low expression in human tissues." (PMID 31480803, 2019). "For this purpose it will be an optimal ligand to target PTH2R overexpressing ovarian cancer cells while sparing PTH1R expressing healthy cells." (PMID 31480803, 2019). "This study is the first to report the expression and function of PTH2R in ovarian cancer." (PMID 35410353, 2022). "Screening and sorting of ovarian cancer data from the GEO database and sequencing data from TCGA (combined with the GTEx dataset) revealed that PTH2R was differentially expressed in the GSE18520, GSE66957 and TCGA-OV datasets; it was significantly highly expresses in tumor tissue." (PMID 35410353, 2022). "In conclusion, PTH2R is expected to become a new molecular marker for ovarian cancer." (PMID 35410353, 2022). "Finally, experimental verification showed that PTH2R gene was highly expressed in ovarian cancer, and PTH2R gene was involved in the proliferation, invasion and metastasis of ovarian cancer cells." (PMID 35410353, 2022). "PTH2R is thus expected to become a new molecular marker for ovarian cancer." (PMID 35410353, 2022). "Comparing the PTH2R gene expression levels in ovarian cancer and normal tissues, and in the ovarian cancer cells and normal ovarian epithelial cells, revealed that the expression of PTH2R was significantly higher in ovarian cancer tissues and cells than in normal ovarian tissues and cells." (PMID 35410353, 2022). "However, PTH2R tends to be overexpressed only in ovarian cancer." (PMID 35410353, 2022). "PTH2R may therefore be useful as a potential biomarker for ovarian cancer in the future." (PMID 35410353, 2022). "The proliferation ability of PTH2R on ovarian cancer cells was detected by CCK-8 assay, revealing that compared with the control group, the decreased expression of PTH2R reduced the A2780 and SKOV3 proliferation activity." (PMID 35410353, 2022). "To date, PTH2R has not been studied in ovarian cancer, however, so here PTH2R was chosen as the study object." (PMID 35410353, 2022).
ovarian carcinoma (continued). "Several receptors have been found to be upregulated in ovarian cancer tissues, including growth hormone releasing hormone receptor (GHRHR), GRPR, leucine-rich repeat-containing G-protein coupled receptor 5 (LGR5), oxytocin receptor (OXTR) and parathyroid hormone 2 receptor (PTH2R)." (PMID 35625966, 2022).
Anxiety (3 papers, 2012 to 2025). Intense feelings of nervousness, tension, or panic often arise in response to interpersonal stresses. "TIP39-positive fibers and PTH2R are widely distributed and found in high densities in key areas associated with stress, fear, and anxiety, including the hypothalamus, amygdala, LS, BST, and mPFC." (PMID 41585794, 2025). "The following will describe the possible mechanism of postpartum anxiety and depression-like behavior caused by the abnormal TIP39/PTH2R system." (PMID 41585794, 2025). "Furthermore, mice lacking TIP39 or the PTH2R demonstrated increased anxiety- and depression-like behaviors 16–17 days but not 7–9 days after a foot shock in elevated-zero maze, open field, light-dark box and forced-swim tests." (PMID 23060860, 2012).
migraine (2 papers, 2022 to 2025). "Collectively, these findings offer new perspectives on class B GPCRs such as PTH1R and PTH2R, emerging as robust and promising candidates for novel clinical targets in conditions like migraine and other painful disorders." (PMID 40297711, 2025). "In summary, the findings of this study present fresh insights into class B GPCRs like PTH1R and PTH2R, standing out as sturdy and promising targets for innovative therapeutic in conditions such as migraine and various painful disorders." (PMID 40297711, 2025). "Other receptors with possible indirect effects on migraine are parathyroid hormone 1 receptor (PTH1R) and PTH2R, which mediates calcium and phosphate homeostasis, and NPY5R that acts as receptor for neuropeptide Y (NPY), PYY, and PYY, and influences eating." (PMID 35453627, 2022).
breast carcinoma (1 paper, 2022). "Although PTH2R was identified as prognostic index in papillary thyroid cancer and breast cancer bone metastases." (PMID 35410353, 2022).
Graves disease (1 paper, 2021). Graves' disease is an autoimmune disorder that leads to overactivity of the thyroid gland (hyperthyroidism).It is caused by an abnormal immune system response that causes the thyroid gland to produce too much thyroid hormones. "In the thyroid, ATP4A and PTH2R variants were only found in Hashimoto’s disease, while SLC9A4 variants were only found in Graves’ disease." (PMID 34944008, 2021).
ovarian disorder (1 paper, 2025). A disease involving the ovary. "Studies have reported that altered expression levels of PTH and PTH2R genes may be associated with ovarian disorders, such as elevated serum parathyroid hormone concentrations in polycystic ovary syndrome patients." (PMID 41154849, 2025).
psoriasis (1 paper, 2016). An autoimmune condition characterized by red, well-delineated plaques with silvery scales that are usually on the extensor surfaces and scalp. "For example, PTH2R was predicted as the target of drugs annotated with ATC code D, and the protein has been found to be associated with psoriasis and psoriatic disorders in TTD." (PMID 26853265, 2016).
vascular dementia (1 paper, 2021). A degenerative vascular disorder affecting the brain. "PTH2R was identified as a hub gene in a weighted co-expression network analysis using transcriptomic data from the frontal lobe and temporal cortex in patients with vascular dementia or AD." (PMID 34654479, 2021).
cancer (3 papers, 2022 to 2026). A tumor composed of atypical neoplastic, often pleomorphic cells that invade other tissues. "It preliminarily demonstrates the mechanism by which melatonin inhibits LUAD by targeting PTH2R, offering crucial experimental evidence and theoretical support for developing precision therapeutic strategies against this cancer." (PMID 41751388, 2026). "The parathyroid hormone type 2 receptor (PTH2R) exhibits differential expression across multiple cancers, yet its role in LUAD remains unclear." (PMID 41751388, 2026).
tumor (2 papers, 2019 to 2022). "Then, tumor samples were further divided into high and low PTH2R expression groups, which allowed PTH2R-related genes and molecular characteristics to be better investigated." (PMID 35410353, 2022). "Subsequently, transwell invasion and migration experiments further demonstrated that PTH2R downregulation significantly reduced the invasion and migration of tumor cells." (PMID 35410353, 2022). "Experiments verified that PTH2R was not only highly expressed in tumor cells and tissues, but also affected the proliferation, invasion, and migration of tumor cells." (PMID 35410353, 2022). "Subsequently, western blot and IHC results also showed that PTH2R protein expression was significantly both higher in tumor than in normal tissues and cells; this result is consistent with the expression trend of PTH2R in RNA-Seq data observed in the previous database." (PMID 35410353, 2022). "In addition, a series of tumor cell function experiments, such as CCK-8, clonogenesis, and transwell assays, showed that PTH2R knockdown significantly inhibited the growth, invasion, and migration of tumor cells." (PMID 35410353, 2022). "A prognostic signature based on RGs (AGTR1, CTGF, FAM3B, IL11, IL17C, PTH2R and SPAG11A) performed moderately in prognostic predictions and correlated with age, tumor stage, metastasis, number of lesions, and tumor burden." (PMID 30661062, 2019).
psychiatric disorder (1 paper, 2021). A disorder characterized by behavioral and/or psychological abnormalities, often accompanied by physical symptoms. "We asked whether the apparent correlation between the age-dependent expression patterns of FZD1 and PTH2R and their dysregulation in ASD is a random observation or can be generalized to other GPCR DEs in ASD or even to other psychiatric disorders." (PMID 34831190, 2021).
PTH2R also shares sentences with these, for which no sentence is quoted: autoimmune disorders (1 paper); Cognitive impairment (1); depression (1); glioblastoma (1); glioma (1); Hashimoto’s disease (1); kidney chromophobe (1); lung adenocarcinoma (1); neuroendocrine disorder (1); osteoporosis (1); painful (1); papillary thyroid cancer (1); polycystic ovary syndrome (1); vitamin D deficiency (1).